UBE2C (ubiquitin conjugating enzyme E2 C)
Description:
Accepts ubiquitin from the E1 complex and catalyzes its covalent attachment to other proteins. In vitro catalyzes 'Lys-11'- and 'Lys-48'-linked polyubiquitination. Acts as an essential factor of the anaphase promoting complex/cyclosome (APC/C), a cell cycle-regulated ubiquitin ligase that controls progression through mitosis. Acts by initiating 'Lys-11'-linked polyubiquitin chains on APC/C substrates, leading to the degradation of APC/C substrates by the proteasome and promoting mitotic exit.
Synonyms: UBCH10; dJ447F3.2
Tractability: Antibody: its Gene Ontology location is reachable by antibodies, with high confidence; the Human Protein Atlas places it where antibodies can reach. PROTAC: UniProt records ubiquitination sites on it; ubiquitination databases record sites on it.
Target class: Enzyme; Transferase
Gene: Protein-coding gene on chromosome 20 (45,812,576 to 45,816,957, forward strand). Ensembl gene ENSG00000175063.
Subcellular location (Human Protein Atlas): Cytosol; Plasma membrane
Pathways (Reactome):
Cell Cycle: APC-Cdc20 mediated degradation of Nek2A; APC/C:Cdc20 mediated degradation of Cyclin B; APC/C:Cdc20 mediated degradation of Securin; APC/C:Cdc20 mediated degradation of mitotic proteins; APC/C:Cdh1 mediated degradation of Cdc20 and other APC/C:Cdh1 targeted proteins in late mitosis/early G1; Autodegradation of Cdh1 by Cdh1:APC/C; Cdc20:Phospho-APC/C mediated degradation of Cyclin A; Conversion from APC/C:Cdc20 to APC/C:Cdh1 in late anaphase; Inactivation of APC/C via direct inhibition of the APC/C complex; Phosphorylation of the APC/C; Regulation of APC/C activators between G1/S and early anaphase; Separation of Sister Chromatids
DNA Replication: Assembly of the pre-replicative complex; CDK-mediated phosphorylation and removal of Cdc6
Cellular responses to stimuli: Senescence-Associated Secretory Phenotype (SASP)
Disease: Aberrant regulation of mitotic exit in cancer due to RB1 defects
Gene expression (Transcription): Transcriptional Regulation by VENTX
Immune System: Antigen processing: Ubiquitination & Proteasome degradation
Metabolism of proteins: Synthesis of active ubiquitin: roles of E1 and E2 enzymes
Gene Ontology:
Molecular function: protein binding; ubiquitin conjugating enzyme activity; ubiquitin-like protein ligase binding; ubiquitin-protein transferase activity; ubiquitin protein ligase activity; ubiquitin-like protein transferase activity
Biological process: anaphase-promoting complex-dependent catabolic process; exit from mitosis; free ubiquitin chain polymerization; positive regulation of exit from mitosis; positive regulation of mitotic metaphase/anaphase transition; proteasome-mediated ubiquitin-dependent protein catabolic process; protein K11-linked ubiquitination; protein K48-linked ubiquitination; protein ubiquitination; ubiquitin-dependent protein catabolic process; positive regulation of ubiquitin protein ligase activity; protein polyubiquitination; regulation of mitotic metaphase/anaphase transition; protein modification by small protein conjugation
Cellular component: anaphase-promoting complex; cytosol; plasma membrane; ubiquitin ligase complex; nucleoplasm
Genetic constraint (gnomAD): Loss-of-function variants: 16 observed, 22.64 expected, observed/expected ratio (o/e) 0.71, 90% interval 0.48 to 1.07. The upper end of that interval is the gene's LOEUF score, 1.07, which puts it in group 4 of 6, group 1 being the genes least tolerant of losing a copy. Missense variants: 192 observed, 227.19 expected, observed/expected ratio (o/e) 0.85, 90% interval 0.75 to 0.95. Synonymous variants: 76 observed, 85.59 expected, observed/expected ratio (o/e) 0.89, 90% interval 0.74 to 1.08.
Homologues: Orthologues: pig UBE2C (98% identical), guinea pig Ube2c (97% identical), rabbit UBE2C (97% identical), rat Ube2c (96% identical), mouse Ube2c (96% identical), tropical clawed frog ube2c (79% identical), zebrafish UBE2C (72% identical), Drosophila melanogaster vih (56% identical). Paralogues in human: UBE2B (36% identical), UBE2A (35% identical), UBE2N (34% identical), CDC34 (31% identical), UBE2NL (31% identical), UBE2T (31% identical), UBE2R2 (29% identical), UBE2G1 (27% identical), UBE2I (27% identical), UBE2K (27% identical), UBE2O (26% identical), UBE2U (26% identical), and 12 more.
Diseases named in the same sentence as UBE2C in open-access papers:
UBE2C is named in the same sentence as 150 diseases in open-access papers, as found by Europe PMC text mining. Sharing a sentence is not in itself a finding about the gene and the disease. The quoted sentences say what the papers report.
breast carcinoma (96 papers, 2007 to 2026). "PILRA, MKI67, and UBE2C, as potential diagnostic and prognostic biomarkers, are anticipated to serve as promising therapeutic targets for the clinical management of both breast cancer and thyroid cancer." (PMID 41328437, 2025). "UBE2C has been found to be upregulated in various types of cancer, including breast cancer, and is considered a potent proto-oncogene associated with tumor malignancy." (PMID 38463168, 2024). "In other words, high levels of UBE2S and UBE2C and decreased Numb expression were associated with a shorter lifespan in breast cancer patients." (PMID 36860312, 2023). "A better understanding of the regulatory mechanisms underlying UBE2S and UBE2C function in breast cancer is expected to identify novel prognostic markers and develop new effective anticancer strategies." (PMID 36860312, 2023). "Poorly differentiated breast cancer tumors are characterized by specific set of over-expressed genes (e.g., UBE2C, CCNB2, CDK1, KIF2C, NDC80, and CCNB2) and are associated with more aggressive tumors and lower survival." (PMID 34300003, 2021). "For instance, high UBE2C expression is associated with poor prognosis in breast cancer, especially basal-like breast cancer." (PMID 32833968, 2020). "We previously reported that UBE2C is significantly associated with poor prognosis in patients with HR+/HER2– breast cancer." (PMID 32039034, 2019). "Taken together, these results show that loss of UBE2C inhibits cell proliferation by affecting cell cycle progression in HR+/HER2– breast cancer cells treated with estrogen." (PMID 32039034, 2019). "UBE2C expression is associated with aggressive thyroid, ovarian and breast carcinomas; colon cancer; and lymphomas." (PMID 24699941, 2014). "Psyrri and colleagues found that elevated UBE2C mRNA expression was associated with poor disease-free and overall survival in breast cancer." (PMID 24489730, 2014). "In this study, we have confirmed that increased expression of UBE2C protein was linked to poor prognosis in N+ breast cancer." (PMID 19513072, 2009). "In recent years, dysregulation of UBE2C has been implicated in a variety of cancers, including breast cancer; however, the underlying mechanisms remain unclear." (PMID 40729680, 2025). "UBE2C showed a great potential as a diagnostic marker for breast cancer, with an AUC of 0.975." (PMID 40729680, 2025). "The UBE2C gene was reported to be highly expressed in a variety of solid tumours and remains an independent adverse prognostic factor for relapse and death in high-risk breast cancer." (PMID 34815392, 2021). "In this study, we further reanalyzed the correlation between UBE2C mRNA expression and clinical outcomes in patients with HR+/HER2– breast cancer, and we investigated the molecular mechanism underlying the role of UBE2C modulation in disease progression in this subgroup of patients." (PMID 32039034, 2019). "We previously showed that UBE2C mRNA expression is significantly associated with poor prognosis only in patients with hormone receptor (HR)+/human epidermal growth factor receptor 2 (HER2)– breast cancer." (PMID 32039034, 2019). "High UBE2C expression is associated with a high degree of malignancy, low differentiation, high metastatic tendency, and poor patient survival in a wide range of solid tumors including breast cancer." (PMID 32039034, 2019). "Ubiquitin-conjugating enzyme E2C (UBE2C), which encodes a member of the E2 ubiquitin-conjugating enzyme family, had been reported to serve momentous roles in various malignancies, including breast cancer, colorectal cancer, and hepatocellular carcinoma." (PMID 30369945, 2018). "Moreover, the expression of both FOXM1 and UBE2C in breast cancer has already been associated with ErbB2 pathway." (PMID 29596365, 2018).
breast carcinoma (continued). "The trophinin-associated protein regulated by TROAP, has been correlated to aggressive clinico-pathological features including tumour high grade and mitotic rate, while the gene UBE2C has been previously recognised as a prognostic marker for high-risk breast cancer patients." (PMID 27341628, 2016). "We wondered whether UBE2C expression was associated with that of other oncogenic genes in breast cancer cells." (PMID 24699941, 2014). "Furthermore, in breast cancer, an increased expression of UBE2C was associated with high tumour grade and cancer progression." (PMID 19513072, 2009). "Similarly, Kim and coworkers showed that UBE2C overexpression could promote the proliferation of breast cancer cells, and UBE2C upregulation is linked with a poor prognosis." (PMID 38637730, 2024). "Therefore, the expression of UBE2C was associated with that of selected carcinogenic genes in breast cancer cells and core biopsies and might be involved in breast cancer tumor formation or migration." (PMID 24699941, 2014). "UBE2C is a member of the ubiquitin conjugating enzyme family, often overexpressed in various cancers, including ovarian, colorectal, and breast cancers." (PMID 41492994, 2026). "The GEPIA and cProSite databases were used to analyze the association between UBE2C and TOP2A, according to mRNA and protein abundance in breast cancer." (PMID 40729680, 2025). "In the present study, we found that UBE2C was aberrantly upregulated in breast cancer and correlated with poor prognosis in patients with breast cancer." (PMID 40729680, 2025). "Taken together, these results indicated that UBE2C was upregulated in breast cancer and correlated with poor prognosis in patients with breast cancer." (PMID 40729680, 2025). "Knockdown of UBE2C significantly inhibited the proliferation, colony formation, migration, and invasion of breast cancer cells." (PMID 40729680, 2025). "The protein level of UBE2C in breast cancer was also significantly upregulated based on the the national cancer institute'sclinical proteomic tumor analysis consortium (CPTAC) and the Human Protein Atlas databases." (PMID 40729680, 2025). "In the present study, UBE2C was identified for the first time as a novel regulator of TOP2A expression in breast cancer." (PMID 40729680, 2025). "Higher expression of UBE2C was correlated with worse prognosis in breast cancer with regards to overall survival (OS) and relapse‐free survival (RFS)." (PMID 40729680, 2025). "Our study revealed that UBE2C is a critical regulator in breast cancer cell proliferation, senescence, and sensitivity to doxorubicin." (PMID 40729680, 2025). "In this study, we showed that UBE2C inhibition suppressed the proliferation of breast cancer cells and induced senescence." (PMID 40729680, 2025). "Taken together, these results indicated that FOXM1 transcriptionally regulated the expression of UBE2C in breast cancer cells." (PMID 40729680, 2025). "In the present study, UBE2C was significantly upregulated in breast cancer and was transcriptionally regulated by FOXM1." (PMID 40729680, 2025). "Inhibition of UBE2C suppressed proliferation, induced senescence, and sensitized breast cancer cells to doxorubicin." (PMID 40729680, 2025). "In the study, UBE2C was found to be significantly overexpressed in breast cancer and transcriptionally regulated by FOXM1." (PMID 40729680, 2025). "The study reveals that UBE2C is a critical regulator of breast cancer cell proliferation, senescence, and sensitivity to doxorubicin." (PMID 40729680, 2025). "Some studies have reported the role of CCNB1, CCNB2, PTTG1, RACGAP1, and UBE2C in cell cycle regulation, aggressive tumor behavior, a poor prognosis, resistance to therapy, and cancer stem cell regulation in breast cancer." (PMID 41009526, 2025). "The expression of UBE2C in breast cancer was also validated using several the gene expression omnibus (GEO) datasets and TCGA database." (PMID 40729680, 2025).
breast carcinoma (continued). "In the present study, UBE2C was found to be markedly upregulated in breast cancer and transcriptionally regulated by FOXM1." (PMID 40729680, 2025). "Taken together, these results indicated that UBE2C knockdown sensitized breast cancer cells to doxorubicin in vitro and in vivo." (PMID 40729680, 2025). "Numerous studies have highlighted the significant role of UBE2C in tumor progression, such as in endometrial cancer, head and neck squamous cell carcinoma, breast cancer, and lung cancer." (PMID 38637730, 2024). "Only MMP11, MYBL2, SFRP1, and UBE2C identified in our study are also featured together as biomarkers in the PAM50 breast cancer 50 gene panel." (PMID 39596491, 2024). "To identify the differential expression of UBE2S, UBE2C, and Numb in breast cancer tissues at the protein level, we resorted to the Human Protein Atlas (HPA) database." (PMID 36860312, 2023). "Taken together, UBE2S and UBE2C were worse prognosis predictors in breast cancer patients as well as in ER+ patients, while Numb showed the opposite prognostic effect." (PMID 36860312, 2023). "UBE2C is thought to promote breast cancer proliferation by activating the AKT/mTOR signaling pathway, a known key player in metastasis." (PMID 37958776, 2023). "UBE2C inhibition sensitizes breast cancer cells to treatment with radiation and doxorubicin (alkylating agent), as well as to anti-hormonal agents such as tamoxifen (estrogen receptor modulator) and letrozole (nonsteroidal aromatase inhibitor)." (PMID 37958776, 2023). "In breast cancer cells, UBE2C silencing inhibits ERK and AKT phosphorylation and increases the levels of phosphorylated PTEN, which acts as a negative regulator of the PI3K/AKT pathway." (PMID 37958776, 2023). "Given above, the expression and prognostic roles of UBE2S, UBE2C, and Numb were evaluated in breast cancer as well as in ER+ breast cancer in this research." (PMID 36860312, 2023). "Next, we found that the expression of UBE2S and UBE2C was upregulated while Numb was downregulated in breast cancer tissues of higher histological grades and pathological stages." (PMID 36860312, 2023). "In contrast, UBE2C knockdown leads to inhibition of proliferation and invasion in breast cancer cells, as well as a decrease of p-AKT, p-mTOR, and hypoxia-inducible factor 1-α (HIF-1α) and an increase of phosphorylated phosphatase and p-PTEN levels." (PMID 37958776, 2023). "We reported overexpression of UBE2S and UBE2C and downregulation of Numb in breast cancer compared with normal breast tissue at both mRNA and protein levels." (PMID 36860312, 2023). "Taken together, we uncover that UBE2S and UBE2C confer a poor prognosis for breast cancer via downregulation of Numb." (PMID 36860312, 2023). "In the present study, we first proposed that UBE2S and UBE2C confer poor prognosis in breast cancer via downregulation of Numb." (PMID 36860312, 2023). "We also sought to determine the correlation between UBE2S, UBE2C, and Numb expression in three common types of breast cancer, namely ER+, HER2+, and triple-negative breast cancer (TNBC)." (PMID 36860312, 2023). "UBE2C inhibition has been shown to increase doxorubicin sensitivity in breast cancer cells in vitro." (PMID 37377594, 2023). "Next, we evaluated the impact of differential mRNA expression of UBE2S, UBE2C, and Numb on the clinical survival of breast cancer patients." (PMID 36860312, 2023). "Breast cancer with higher UBE2S or UBE2C levels and lower Numb expression is correlated with a worse prognosis, providing potential biomarkers for BC therapeutics." (PMID 36860312, 2023).